NDUFS5 (NADH:ubiquinone oxidoreductase subunit S5)
Description:
Accessory subunit of the mitochondrial membrane respiratory chain NADH dehydrogenase (Complex I), that is believed not to be involved in catalysis. Complex I functions in the transfer of electrons from NADH to the respiratory chain. The immediate electron acceptor for the enzyme is believed to be ubiquinone.
Synonyms: CI-15k; CI15K
Tractability: Small molecule: an approved drug acts on it; a structure with a bound ligand is known. Antibody: UniProt places it where antibodies can reach, with high confidence. PROTAC: ubiquitination databases record sites on it; its protein half-life has been measured.
Gene: Protein-coding gene on chromosome 1 (39,026,318 to 39,034,636, forward strand). Ensembl gene ENSG00000168653.
Subcellular location: Mitochondrion inner membrane; Mitochondrion intermembrane space
Pathways (Reactome):
Metabolism: Complex I biogenesis; Respiratory electron transport
Gene Ontology:
Molecular function: protein binding; NADH dehydrogenase (ubiquinone) activity
Biological process: mitochondrial respiratory chain complex I assembly; aerobic respiration; mitochondrial electron transport, NADH to ubiquinone; proton motive force-driven mitochondrial ATP synthesis; proton transmembrane transport
Cellular component: mitochondrial inner membrane; mitochondrion; respiratory chain complex I; mitochondrial intermembrane space
Genetic constraint (gnomAD): Loss-of-function variants: 7 observed, 12.03 expected, observed/expected ratio (o/e) 0.58, 90% interval 0.33 to 1.09. The upper end of that interval is the gene's LOEUF score, 1.09, which puts it in group 4 of 6, group 1 being the genes least tolerant of losing a copy. Missense variants: 148 observed, 147.35 expected, observed/expected ratio (o/e) 1, 90% interval 0.88 to 1.15. Synonymous variants: 38 observed, 46.22 expected, observed/expected ratio (o/e) 0.82, 90% interval 0.63 to 1.08.
Homologues: Orthologues: chimpanzee NDUFS5 (100% identical), dog NDUFS5 (80% identical), pig NDUFS5 (79% identical), rabbit NDUFS5 (77% identical), guinea pig NDUFS5 (75% identical), mouse Ndufs5 (75% identical), rat Ndufs5 (74% identical), rat Ndufs5-ps1 (74% identical), rat Ndufs5-ps2 (74% identical), zebrafish ndufs5 (64% identical), tropical clawed frog ndufs5 (50% identical).
Diseases named in the same sentence as NDUFS5 in open-access papers:
NDUFS5 is named in the same sentence as 23 diseases in open-access papers, as found by Europe PMC text mining. Sharing a sentence is not in itself a finding about the gene and the disease. The quoted sentences say what the papers report.
endometritis (3 papers, 2024 to 2025). An acute or chronic, usually bacterial infectious process affecting the endometrium. "Buffaloes with endometritis showed significantly decreased levels of expression of the NDUFS5, RXFP1, TGF-β, CAT, SOD3, and GPX transcription factors." (PMID 40266925, 2025). "In the buffaloes affected by endometritis, the expression levels of the RXFP1, NDUFS5, TGF-β, SOD3, CAT, and GPX genes were significantly reduced." (PMID 39195794, 2024). "The RXFP1, NDUFS5, TGF-β, SOD3, CAT, and GPX genes were expressed at substantially lower levels in endometritis-affected buffaloes." (PMID 38459095, 2024).
myopia (2 papers, 2017 to 2023). "A meta-analysis of transcriptome data reported upregulation of the NDUFS5 gene in late stage of myopia, which encoded a subunit of complex I." (PMID 38136985, 2023). "In addition to complement pathway and structural genes, five genes encoding mitochondrial ribosomal proteins and one gene encoding a subunit of mitochondrial complex I (NDUFS5) were up-regulated in late myopia." (PMID 28852117, 2017).
esophageal cancer (1 paper, 2021). A primary or metastatic malignant neoplasm involving the esophagus. "Using The Cancer Genome Atlas database, we analyzed the relationships of NDUFA1, NDUFS5, and COX6B1 expression with esophageal cancer." (PMID 34226508, 2021).
gastric cancer (1 paper, 2023). A primary or metastatic malignant neoplasm involving the stomach. "Besides, the elevated level of NDUFS5 is associated with good survival in lung adenocarcinoma, but related to significantly reduced time to first progression in gastric cancer." (PMID 37469574, 2023).
glioma (1 paper, 2021). A benign or malignant brain and spinal cord tumor that arises from glial cells (astrocytes, oligodendrocytes, ependymal cells). "In addition, we found that four of the candidate tumor gene biomarkers (NDUFS5, NDUFA1, NDUFA13, and NDUFB8) belong to the NADH ubiquinone oxidoreductase subunit gene family, so we inferred that this gene family may be strongly related to glioma." (PMID 34863158, 2021).
heart failure (1 paper, 2020). Inability of the heart to pump blood at an adequate rate to meet tissue metabolic requirements. "Another report demonstrated that AF-HF001, a clinical drug candidate for heart failure, reversed the up-regulation of NDUFS5 expression in H9c2 rat cardiomyocytes and attenuated ROS production and myocardial cell apoptosis." (PMID 32138671, 2020).
multiple sclerosis (1 paper, 2021). A progressive autoimmune disorder affecting the central nervous system resulting in demyelination. "Dysfunction of Ndufs5 due to its SNP haplotype was associated with multiple sclerosis." (PMID 33546359, 2021).
type 2 diabetes (1 paper, 2025). "Among these, mitochondrial-associated proteins such as the NADH:ubiquinone oxidoreductase subunit proteins NDUFS5, NDUFA10 and NDUFS8 were downregulated in type 2 diabetes." (PMID 40295335, 2025).
tumor (5 papers, 2020 to 2023). "The top genes in cold tumor are ARF1, PDIA3, ALDOA, FKBP2, NDUFS5, NDUFC1, COX7A2, C14orf2, LNX1, and BTBD6." (PMID 33816503, 2021). "The results indicated that cloperastine inhibited tumor growth was by suppressing NDUFA1, NDUFS5, and COX6B1 expression." (PMID 34226508, 2021). "In addition, we found that four (NDUFS5, NDUFA1, NDUFA13, and NDUFB8) of the candidate tumor gene biomarkers belong to the NADH ubiquinone oxidoreductase subunit gene family." (PMID 34863158, 2021).
neurodegenerative disease (2 papers, 2024 to 2025). A disorder of the central nervous system characterized by gradual and progressive loss of neural tissue and neurologic function. "GO and KEGG analyses of ME7 also identified upregulation of genes related to mitochondrial oxidative phosphorylation, including NDUFS6, NDUFA13, NDUFB7, NDUFA3, and NDUFS5, which are involved in a variety of neurodegenerative diseases." (PMID 37971544, 2024). "The mitochondrial dysfunction in the neurodegenerative diseases cluster (Cluster 4) comprises 95 genes, including several key mitochondrial protein genes acting as pivotal hub genes, such as Sdhb, Ndufa4, Ndufb4c, Ndufb4b, Ndufv3, Ndufa9, Ndufc1, Ndufs5, Ndufb4, Ndufa12, Ndufa11, and Ndufb1." (PMID 41294802, 2025).
NDUFS5 also shares sentences with these, for which no sentence is quoted: Parkinson disease (3 papers); Alzheimer disease (2); cancer (2); amyotrophic lateral sclerosis (1); breast carcinoma (1); cardiomyopathy (1); Huntington disease (1); invasive breast carcinoma (1); lactic acidosis (1); leukemia (1); lung adenocarcinoma (1); non-alcoholic fatty liver disease (1); serous ovarian adenocarcinoma (1).